HIF1A (hypoxia inducible factor 1 subunit alpha)
Diseases named in the same sentence as HIF1A in open-access papers (continued):
Sharing a sentence is not in itself a finding about the gene and the disease.
tumor (continued). "Because of the mutations in succinate dehydrogenase (SDH), succinate is abnormally accumulated, promoting tumor growth and metastasis by stabilizing HIF-1α and activating SUCNR1 signaling." (PMID 41236698, 2025). "Hypoxia itself promotes cytokine production, and IL-6 can further amplify the hypoxic response via STAT3 and HIF-1α stabilization, forming a detrimental positive feedback loop that exacerbates tumor progression." (PMID 41302515, 2025). "Spatial differences in oxygen levels within primary tumors and tumor heterogeneity result in some in situ tumor samples showing concurrent low expression of HIF-1α and DSG216." (PMID 41381723, 2025). "Hypoxia‐inducible factor (HIF), a central regulator of cellular metabolism and hypoxia adaptation, plays a pivotal role in tumor metabolic reprogramming and macrophage M2 polarization, with HIF‐1α being the key mediator." (PMID 41360672, 2025). "This abnormal HIF‐1α activation helps tumor cells grow in a hypoxic environment and enhances their resistance to treatment." (PMID 40944417, 2025). "HIF-1α promotes the polarization of macrophages towards the M2 phenotype, which supports tumor growth and suppresses immune responses." (PMID 39981236, 2025). "HIF-1α regulates fatty acid oxidation in Tregs, supporting their immunosuppressive roles within hypoxic tumor niches." (PMID 41050070, 2025). "Under normoxic conditions, the increase in glutamine consumption leads to an increase in intracellular ammonia concentration, which results in stabilizing HIF-1α in different tumor cell lines." (PMID 40358197, 2025). "TME is also hypoxic, which can down-regulate the expression of activating receptors NKG2D and induce the release of HIF1α in tumor-infiltrating NK cells, thereby reducing their antitumor response and IFN-γ production." (PMID 40043109, 2025). "Under hypoxic conditions, HIF‐1α prompts tumor cells to secrete PDGF, which subsequently mediates CAF resistance to ripretinib via the PDGFR signaling pathway." (PMID 41164803, 2025). "Tumor lactate accumulation also promotes angiogenesis and cancer stemness by enhancing lactylation of HIF1α." (PMID 41303712, 2025). "HIF-1α, as an oxygen-dependent transcriptional activator that promotes mammalian development and accelerates tumor progression, can enhance tumor invasion by altering metabolic pathways and inducing the production of pro-angiogenic factors." (PMID 40704062, 2025). "STING can regulate anti-tumor immunity by stabilizing the expression of HIF-1α, increasing glycolysis and reducing oxidative phosphorylation in macrophages." (PMID 41372134, 2025). "HIF-1α alters the tumour microenvironment and promotes angiogenesis and glycolysis, whereas RUNX2 is an important bone transcription factor." (PMID 40806771, 2025). "Concurrent HIF-1α-mediated upregulation of anti-apoptotic Bcl-2/Survivin and suppression of Bax expression enhances tumor cell survival." (PMID 41357522, 2025). "Such degradation leads to the accumulation and stabilization of HIF‐1α, thereby enhancing the growth, invasive capacity, and metastatic potential of tumor cells." (PMID 41427004, 2025). "In the glioma microenvironment, hypoxic or pseudohypoxic conditions are frequently observed within the tumor core, leading to the stabilization and activation of key transcription factors, including Hypoxia-inducible factor-1α (HIF-1α) and MYC." (PMID 41463052, 2025). "For instance, nanoparticles combining HIF-1α inhibitors, ICIs, and oxygen-releasing agents have demonstrated synergistic effects in reducing tumor growth and enhancing immune responses." (PMID 39981236, 2025). "Mechanistically, this was linked to impaired expression of PLOD2 which is regulated by HIF-1α and critical for structuring the extracellular matrix in a way that facilitates tumor invasion." (PMID 41174561, 2025). "This can be explained by the fact that hypoxia occurs in the tumor environment during tumor growth, so that HIF-1α activity increases." (PMID 40429943, 2025).
tumor (continued). "HIF-1α, a calcium ion-sensitive factor, has also been confirmed to participate in tumor cell metastasis by promoting epithelial‒mesenchymal transition (EMT) and angiogenesis." (PMID 40438141, 2025). "This suggests that this combination therapy approach is able to target the PI3K/AKT/HIF-1α pathway to a greater extent, thereby achieving an anti-tumor effect." (PMID 41041327, 2025). "HIF-1α can induce glycolysis, immunosuppression, tumor angiogenesis, and necroptosis in response to hypoxia." (PMID 40171017, 2025). "A central mechanism of tumor adaptation to hypoxic conditions is the stabilization and activation of hypoxia-inducible factor 1α (HIF-1α), which governs the expression of pro-angiogenic and pro-survival genes." (PMID 41302515, 2025). "Other key upregulated pathways including cell‐cycle and HIF1α, highlighting the roles in tumor proliferation, survival, and aggressiveness." (PMID 39548807, 2025). "We discovered that hirudin inhibits tumor cell clustering by impairing DSG2-mediated desmosome through binding to HIF-1α, although the specific binding site remains unvalidated." (PMID 41381723, 2025). "In tumor cells, enhanced expression of fatty acid binding proteins (FABPs) is also observed, and their expression is stimulated by HIF1α." (PMID 40723225, 2025). "Hypoxia-induced HIF-1α upregulates PD-L1 expression on tumor cells and antigen-presenting cells, leading to T cell exhaustion—a state characterized by reduced proliferation, cytokine production, and cytotoxicity." (PMID 39981236, 2025). "Preclinical studies indicate that HIF-1α inhibitors (e.g., PX-478, acriflavine) suppress tumor hypoxia adaptation and angiogenesis while enhancing chemosensitivity." (PMID 40406267, 2025). "In OC, hypoxia-driven HIF-1α signaling enhances tumor aggressiveness by promoting CSC-like traits, chemoresistance, and EMT." (PMID 41373772, 2025). "This review systematically summarizes the role of HIF-1α as the central regulator of tumor-derived exosomes under hypoxic conditions." (PMID 40612677, 2025). "Meanwhile, HIF-1α plays a pivotal role in modulating the biogenesis of these circRNAs, thereby impacting tumor growth and metastasis through their intricate interplay with miRNAs." (PMID 40004471, 2025). "The WWOX/HIF1A axis emerges as a central regulator of tumour metabolism and progression across diverse malignancies." (PMID 41007296, 2025). "In T‐cell acute lymphoblastic leukaemia (T‐ALL), USP20 has been identified as a super‐enhancer‐regulated driver gene that promotes tumour cell survival by deubiquitinating and stabilizing HIF1A." (PMID 41261048, 2025). "Given the complexity of the OCCC TME, therapeutic strategies that combine ICIs with agents targeting key molecules implicated in tumor aggressiveness such as VEGF, HIF-1α, IL-6, IL-10, PI3K, and HDAC6 show considerable promise." (PMID 41383608, 2025). "HIF-1α is often upregulated in the hypoxic conditions typical of NB, which facilitates tumor cell survival and promotes angiogenesis." (PMID 40429864, 2025). "The TNBCvax groups also demonstrated a notable decrease in tumor weight relative to the HIF-1α and IGF-1R groups." (PMID 40969744, 2025). "Hypoxia, for instance, also promotes GC exosome release through a HIF-1α-dependent pathway, impacting tumor development and metastasis." (PMID 40771798, 2025). "ATM’s role extends to hypoxic tumour microenvironments, where it stabilises hypoxia-inducible factor 1-alpha (HIF1α)." (PMID 40256842, 2025). "Redistributed M2-type macrophages induced by lactate enhance tumor immune evasion by increasing the proportion of PD-L1+TAMs through HIF-1α-mediated signaling." (PMID 39897050, 2025). "HIF-1α potently induces PD-L1 expression on tumor cells, resulting in robust suppression of T cell activity and subsequent inhibition of the anti-tumor immune response." (PMID 41153831, 2025).
tumor (continued). "The elevated expression of xCT is also significantly associated with the overexpression of HIF1α, programmed death ligand 1 (PD-L1), colony-stimulating factor 1 (CSF1), tumour-associated macrophage (TAM) and myeloid-derived suppressor cell (MDSC) infiltration." (PMID 41154605, 2025). "Based on our results from the tumor and surrounding healthy tissue samples, HIF1A emerged as the primary determinant of EPO, EPOR and JAK2/STAT5A signaling pathway expression in ccRCC." (PMID 40332447, 2025). "In our study, we found PGK1 was upregulated in advanced tumour tissues which underwent much more hypoxia and HIF‐1α expression." (PMID 40534132, 2025). "Ongoing research focuses on small-molecule inhibitors of HIF-1α, nanoparticle-mediated drug delivery systems for targeted inhibition, and metabolic reprogramming strategies to mitigate hypoxia-induced tumor aggressiveness." (PMID 40136686, 2025). "Paradoxically, ROS upregulate PD-L1 on surviving tumor cells through NF-κB and HIF-1α pathways, creating a therapeutic vulnerability for anti-PD-L1 antibodies." (PMID 41209702, 2025). "HIF-1α promotes a metabolic shift from oxidative phosphorylation to glycolysis—known as the Warburg effect—allowing tumor cells to maintain energy production despite oxygen deficiency." (PMID 41008845, 2025). "Tumor‐derived lactate activates HIF‐1α/NF‐κB signaling, inducing PD‐L1 expression on tumor cells and promoting immune evasion." (PMID 40904700, 2025). "HIF-1α plays a crucial role in tumor survival and progression and is elevated in over half of primary human cancers and their metastases." (PMID 40362444, 2025). "The Pt nanoenzyme increases oxygen production in response to the elevated H2O2 levels within the tumor site and effectively lowers the condition of tumor hypoxia and modulates the production of hypoxia-inducible factor (HIF-1α)." (PMID 39830015, 2025). "RBX1 is a component of the VHL tumor suppressor complex, which ubiquitinates HIFα subunits (HIF1α, HIF2α, and HIF3α) and targets them for degradation under normoxic conditions." (PMID 40436847, 2025). "Conversely, tumor‐derived glutamine depletion forces TAMs to break down lipids through β‐oxidation, releasing acetyl‐CoA, which stabilizes HIF‐1α in cancer cells and promotes their invasive potential." (PMID 40904700, 2025). "LW6 facilitates the degradation of HIF-1α through the proteasome pathway, consequently restricting tumor adaptation to hypoxic conditions." (PMID 40136686, 2025). "Polysaccharides and triterpenes in medicinal mushrooms, such as ganoderic acids from Ganoderma lucidum, inhibit angiogenesis by downregulating VEGF and HIF-1α expression, thereby limiting tumor vascularization and nutrient supply." (PMID 40290037, 2025). "The role of FGFR2 and HIF1A signaling was further validated in subcutaneous xenograft and orthotopic tumor metastasis models." (PMID 40225580, 2025). "A hypoxic tumor microenvironment (TME) induces the accumulation of hypoxia-inducible factor 1 alpha (HIF-1α), which blocks the activation of the NLRP3 inflammasome and the necrosome." (PMID 40809021, 2025). "In the hypoxic core of the tumor, 2HG accumulation drives the shift toward glycolysis and stabilizes the expression of HIF1α, further upregulating genes involved in glycolysis, angiogenesis, and pH regulation." (PMID 39859381, 2025). "The stabilization of HIF-1α in CD4+ T cells improves the effect of anti-PD-1 therapy to reduce tumor growth and patient survival." (PMID 41413686, 2025). "In the tumors divided as HIF1A-positive and HIF1A-negative, statistical significance in terms of expression was observed particularly in the HIF1A-positive tumor (p = 0.041)." (PMID 40332447, 2025). "Our study offers new insights into the molecular mechanisms of TFE3‐RCC, highlighting the pivotal role of the PRCC‐TFE3/HIF1α/SREBP1 axis in tumor development and progression." (PMID 39807625, 2025).
tumor (continued). "Wogonin suppresses tumor development and the generation of HIF‐1α, glycolytic enzymes, and PI3K/AKT, highlighting its potential as an effective treatment against hypoxia‐induced chemoresistance." (PMID 40740483, 2025). "Overexpression of HIF-1α decreases overall survival, disease-free survival, and chemotherapy response and promotes tumour stage and metastasis." (PMID 40806771, 2025). "Although WWOX is recognized as a tumour suppressor, our analyses reveal a paradoxical association with poorer outcomes in high WWOX/HIF1A ratio groups, necessitating deeper mechanistic exploration." (PMID 41007296, 2025). "The MCS exhibited improved viability and a gene expression profile associated with aggressive tumor characteristics, including increased expression of genes linked to cell survival and motility, such as COL1A1, MSN, HIF1A, TUBB, and ACTB." (PMID 41516217, 2025). "HIF-1α has been demonstrated to play a multifaceted regulatory role in natural killer (NK) cell metabolism, anti-tumor immunity, and infection response under hypoxic conditions." (PMID 40791591, 2025). "The significance of HIF expression in TAMs can also not be overstated for tumor angiogenesis, as supported by the observation that knockout of HIF-1α in TAMs resulted in curtailed angiogenesis and a reduction in tumor burden in breast cancer." (PMID 40083710, 2025). "Agents such as PX-478 have shown efficacy in preclinical PCa models by inhibiting HIF-1α expression, reducing angiogenesis, and impairing tumour growth." (PMID 40806577, 2025). "Through its regulation of genes involved in angiogenesis, metabolism, and immune modulation, HIF-1α drives critical aspects of tumor progression." (PMID 39981236, 2025). "This creates a hypoxic environment within the tumor, activating HIF-1α, promoting the survival and growth of tissue SCs, and even inducing angiogenesis." (PMID 41294748, 2025). "Tumor hypoxia is a key regulator of HIF-1α and HIF-2α expression, driving their upregulation in response to oxygen deprivation." (PMID 40443737, 2025). "HIF-1α is widely recognized as a critical effector molecule that enables cells to adapt to hypoxic stress and regulates tumor glycolytic metabolism." (PMID 40032849, 2025). "Taking tea polyphenol epigallocatechin gallate (EGCG) as an example, it can significantly reduce the levels of VEGF-A and HIF-1α secreted by tumor cells and inhibit tumor angiogenesis and nutrient supply, thus effectively hindering tumor growth and metastasis." (PMID 40808836, 2025). "We established that tumours with low WWOX/HIF1A ratios exhibit elevated ROS levels and hypoxia, which together impair DNA repair and promote genomic instability." (PMID 41007296, 2025). "Tumor cells highly express hypoxia-inducible factor-1α (HIF-1α), which promotes the expression of matrix metalloproteinases (MMPs) and a disintegrin and metalloproteinases (ADAMs)." (PMID 40563539, 2025). "These DFs specifically suppress HIF-1α expression of tumor cells, thereby potentiating both chemotherapy and SDT outcomes." (PMID 40852643, 2025). "Mechanistically, in the hypoxic tumor microenvironment, HIF-1α promotes angiogenesis and tumor invasion and directly promotes OTUD6B transcription." (PMID 41050073, 2025). "Studies have found that the expression level of HIF-1α is positively correlated with tumor invasion depth, size, degree of differentiation, and cell invasion and metastasis of GC." (PMID 40458722, 2025). "These metabolites inhibit prolyl hydroxylases, stabilizing HIF-1α and promoting tumor angiogenesis and growth." (PMID 40724998, 2025). "Hypoxia leads to HIF-1α stabilization, which encourages glycolysis in tumor cells and drug resistance." (PMID 40852643, 2025). "Several studies have demonstrated that pentacyclic triterpenoids exert significant inhibitory effects on the HIF-1α signaling pathway, a critical regulator of tumor adaptation to hypoxic stress and angiogenesis." (PMID 41373772, 2025).
tumor (continued). "For instance, HIF-1α regulates the recruitment and polarization of macrophages, driving them towards an immunosuppressive M2 phenotype that promotes tumor progression." (PMID 39981236, 2025). "HIF-1α reduces the expression of activating receptors on NK cells, impairing their ability to recognize and kill tumor cells." (PMID 39981236, 2025). "The tumor-suppressive roles of HIF-1α in clear cell renal cell carcinoma (ccRCC) are mediated by the initiation of pro-apoptotic genes (BNIP3, BNIP3L) and inhibition of c-Myc function." (PMID 41451091, 2025). "The lactate, produced also by tumor cells, activates HIF-1α, enhancing the expression of pro-tumorigenic genes [including VEGFA and Arginase 1 (ARG1)]." (PMID 40868256, 2025). "Hypoxia not only reduces ROS production but also upregulates hypoxia-inducible factor 1α (HIF-1α), promoting tumor survival and angiogenesis." (PMID 40235732, 2025). "According to our data, short-term exposure of tumor cells to low oxygen and adequate nutrition is crucial for full HIF1A activation, which supports tumor growth in the beginning." (PMID 40332447, 2025). "The hypoxic tumor microenvironment drives malignant progression through HIF-1α-mediated upregulation of vascular endothelial growth factor (VEGF) and glycolytic enzymes." (PMID 41357522, 2025). "In breast cancer, the transcription factor ZEB1 promotes macrophage glycolysis via the PI3K/Akt/HIF-1α pathway, facilitating their shift to a pro-tumor state and reinforcing immunosuppression within the TME." (PMID 41200171, 2025). "Combining HIF-1α inhibitors with angiogenesis blockers, metabolic modulators, or adoptive T cell therapies can synergistically enhance anti-tumor responses." (PMID 39981236, 2025). "One of such mechanisms which controls cellular reactions to low oxygen levels, a prevalent situation in the tumor microenvironment is HIF-1α (hypoxia-inducible factor 1α) oncogenic pathway." (PMID 40205002, 2025). "HIF-1α can also be up-regulated by the E3 ligase macrophage-erythroblast attacher, leading to the proliferation of tumor cells and elevated migration capacity in glioblastoma." (PMID 39759114, 2025). "As an essential regulator widely expressed in tumor tissues, HIF-1α acts as a trigger for numerous biological activities and participates in all stages of tumor progression." (PMID 40534881, 2025). "Ginsenoside Rh2 inhibits the aerobic glycolysis of tumors, including the uptake of glucose and the production of lactate, by targeting and down-regulating the expression of HIF-1α, which significantly inhibits tumor proliferation and migration." (PMID 41585262, 2025). "The hypoxic microenvironment within the tumor stabilizes hypoxia-inducible factors (HIF-1α/2α), which act as key transcription factors in the adaptation of cells to low oxygen." (PMID 40806546, 2025). "TSGA10 and Hypoxia-inducible factor 1-alpha (HIF-1α—a protein that helps cancer cells thrive in low oxygen) regulate each other, creating a balance that shapes tumor behavior." (PMID 40507237, 2025). "IL6 via the JAK/STAT3 pathway enhances the expression of hypoxia-inducible factor 1-alpha (HIF1α) under hypoxic and acidic conditions at tumor sites, leading to increased VEGF-A expression, which drives neovascularization and angiogenesis." (PMID 40427188, 2025). "HIF-1α supports tumor cell adaptation to hypoxic conditions by regulating several key enzymes in glucose metabolism." (PMID 40443737, 2025). "HIF-1α overexpression also enhances tumor aggressiveness by promoting EMT, facilitating genetic instability, suppressing apoptosis, and exacerbating resistance to chemotherapy and radiotherapy." (PMID 40606973, 2025). "HIF-1α is an oxygen-dependent transcriptional activator crucial in tumor angiogenesis and mammalian development." (PMID 39859448, 2025). "Hypoxic and acidic TME conditions also upregulate exosome biogenesis (e.g., via HIF-1α signaling), increasing release of immunosuppressive exosomes from tumor cells." (PMID 40941035, 2025).